ERVV-2 (endogenous retrovirus group V member 2, envelope)
Synonyms: ENVV2; HERV-V2
Tractability: Antibody: UniProt predicts a signal peptide or a membrane-spanning region.
Gene: Protein-coding gene on chromosome 19 (53,044,740 to 53,051,680, forward strand). Ensembl gene ENSG00000268964.
Subcellular location: Membrane
Subcellular location (Human Protein Atlas): Cytosol; Centrosome
Gene Ontology:
Cellular component: membrane
Genetic constraint (gnomAD): Loss-of-function variants: 1 observed, 3.05 expected, observed/expected ratio (o/e) 0.33, 90% interval 0.12 to 1.45. That is too few expected variants to judge how well the gene tolerates losing a copy. Missense variants: 113 observed, 195.07 expected, observed/expected ratio (o/e) 0.58, 90% interval 0.5 to 0.68. Synonymous variants: 45 observed, 73.68 expected, observed/expected ratio (o/e) 0.61, 90% interval 0.48 to 0.78.
Homologues: Orthologues: chimpanzee ERVV-2 (99% identical), macaque ERVV-2 (94% identical), macaque ERVV-1 (88% identical), chimpanzee ERVV-1 (85% identical). Paralogues in human: ERVV-1 (86% identical), ERV3-1 (13% identical), ERVW-1 (11% identical), ERVFRD-1 (10% identical), ERVMER34-1 (9% identical).
Diseases named in the same sentence as ERVV-2 in open-access papers:
ERVV-2 is named in the same sentence as 2 diseases in open-access papers, as found by Europe PMC text mining. Sharing a sentence is not in itself a finding about the gene and the disease.
ERVV-2 shares sentences with these, for which no sentence is quoted: tumor (2 papers); infection (1).